TLR4 (toll like receptor 4)
Diseases named in the same sentence as TLR4 in open-access papers (continued):
Sharing a sentence is not in itself a finding about the gene and the disease.
pulmonary fibrosis (continued). "The adverse effect of TLR4 activation has also been confirmed in bleomycin-induced, LPS-induced pulmonary fibrosis models." (PMID 33466366, 2021). "Expression of TLR4 and its endogenous ligands is elevated in skin biopsies of SSc, and dermal and lung fibrosis was attenuated in bleomycin-treated TLR knockout mice." (PMID 33809015, 2021). "While studies have looked at the effect of anti-TLR4 in stopping pulmonary fibrosis, many have failed." (PMID 34258628, 2021). "Toll-like receptor 4 (TLR4) was reported to mediate autophagy in the pathological process of pulmonary fibrosis." (PMID 33746598, 2021). "Not only do tenascin-C-deficient mice have an attenuated response to bleomycin-induced lung fibrosis, but this process has also been shown to be TLR4 dependent." (PMID 34258628, 2021). "Another category of TLR4 agonists that have recently been identified to be involved in the progression of pulmonary fibrosis consists of S100 proteins." (PMID 34258628, 2021). "While the research in therapeutic approaches to pulmonary fibrosis is ongoing, treatment strategies targeting the DAMPs, TLR4, and proinflammatory cytokines pathway have shown promising results in preclinical models." (PMID 34258628, 2021). "The pulmonary fibrosis was ameliorated by TLR4 knockout in murine models of scleroderma, as well as in mice with TLR4 deleted using small hairpin RNA (shRNA)." (PMID 32679721, 2020). "The collective data indicate miR-135a restrains NF-κB activation probably through targeting TLR4 to alleviate silica-induced inflammatory response and pulmonary fibrosis." (PMID 32617074, 2020). "Recently, it has been revealed that activated TLR4 improved lung function and pulmonary fibrosis in the BLM-induced mouse model, which was abolished by TLR4 inhibitor TAK-242." (PMID 32724454, 2020). "Taken together, our data indicate that miR-135a which is suppressed following silica inhalation alleviates the pulmonary fibrosis through targeting TLR4 to inhibit the NF-κB pathway." (PMID 32617074, 2020). "Subsequent experiments sought to explore the role of TLR4 in lung fibrosis, a major fibrotic complication of SSc." (PMID 30405628, 2018). "The severity of AHR and pulmonary fibrosis was decreased and the prognosis improved by inhibiting TLR4 expression." (PMID 25875290, 2015). "In conclusion, our study provides evidence that LPS can promote lung fibroblast proliferation via TLR4 signaling, perhaps accelerating pulmonary fibrosis in the early stages of ALI/ARDS." (PMID 22563417, 2012). "LPS-mediated activation of the TLR4 signaling pathway involves several key pathways associated with ALI/ARDS and pulmonary fibrosis, including the PI3K-Akt pathways." (PMID 22563417, 2012). "In this study, we used the lentivirus-mediated RNA interference technique to inhibit TLR4 gene expression in mouse lung tissue in order to observe lung fibroblasts activation, pulmonary fibrosis initiation, and progression during LPS-induced ALI." (PMID 20017955, 2009). "As a critical mediator of tissue repair and remodeling, hyaluronic acid not only inhibits cellular apoptosis but promotes the proliferation and regeneration of surfactant protein C-positive alveolar progenitor cells through TLR4 activation, thereby inhibiting pulmonary fibrosis in mice." (PMID 41293166, 2025). "In this context, we may hypothesize that calprotectin released by activated immune cells promotes TLR4 signaling with consequent production of TGFβ, which triggers fibroblast proliferation, leading to skin and pulmonary fibrosis." (PMID 40362527, 2025). "It has been previously demonstrated that TLR4 signaling in SSc patients induces the production of transforming growth factor β (TGFβ), which triggers fibroblast proliferation, with consequent development of skin and pulmonary fibrosis." (PMID 40362527, 2025).
pulmonary fibrosis (continued). "Thus, moderate-intensity aerobic exercise (60 min/day, five times/week for 4 weeks) attenuates silica-induced lung fibrosis by inhibiting the TLR4-TNF-α, SRB-NLPR3, TGF-β1, and IL-17A/CXCL5/CXCR2 signaling pathways." (PMID 39796197, 2025). "Additionally, APs have been reported to modulate GM and alleviate pulmonary fibrosis by inhibiting the TLR4/NF-κB signaling." (PMID 41422246, 2025). "Additionally, Wang and colleagues reported that, aside from downregulating TGF-β1/Smad3, resveratrol alleviated pulmonary fibrosis by downregulating lipopolysaccharide (LPS)/toll-Like Receptor 4 (TLR4)/Nuclear factor kappa B (NF-κB) signaling pathways in rats." (PMID 38474385, 2024). "Furthermore, TLR4 activation expedites the resolution of acute inflammation, effectively reverses established pulmonary fibrosis, enhances lung function, and rescues mice from mortality." (PMID 39165378, 2024). "Furthermore, treatment with citrullinated vimentin mediates development and progression of lung fibrosis through Toll-Like Receptor 4 (TLR4)-dependent nuclear factor kappa-light-chain-enhancer of activated B cells (NF-κB) activation in mice." (PMID 38155185, 2023). "It was found that the mRNA and protein level of TLR4 in A549 cells was significantly lower than that in HLF normal lung fibrosis cells, which to some extent mean that TLR4 could inhibit tumors." (PMID 37553698, 2023). "While in obese individuals significant lower methylation of CpGs in the first exon of the TLR4 were observed, therefore these evidence indicated that HFD mediated promoter DNA demethylation contributed to the up-regulation of TLR4 which promoted the apoptosis of AECs and lung fibrosis." (PMID 36979493, 2023). "Moreover, Gal-3 seems to have the ability to bind and activate TLR4 and subsequently induced lung fibrogenesis, while fibroblast-specific deletion of TLR4 in mice induced a significant reduction in lung fibrosis." (PMID 35897786, 2022). "Therefore, the suppression of inflammation through the TLR4/MyD88/NF-κB pathway in an early stage of the fibrosis process can effectively improve lung fibrosis." (PMID 35178456, 2022). "The results showed that HSM could effectively inhibit excessive macrophage autophagy in BLM-induced pulmonary fibrosis mouse model, and the TLR4/NF-κB signaling pathway was required for HSM effect on macrophage autophagy." (PMID 33746598, 2021). "Oppositely, another study suggests knockout of TLR4 may aggravate silica-induced pulmonary fibrosis." (PMID 33466366, 2021). "Furthermore, a growing body of evidence suggests that blocking other DAMPs that also stimulate TLR4 can ameliorate pulmonary fibrosis." (PMID 34367191, 2021). "Currently, the functional role of TLR4 in silica-induced pulmonary fibrosis is controversial." (PMID 33466366, 2021). "Moreover, TLR4 has been associated to fibroblast activation and the subsequent lung fibrosis while fibroblast-specific deletion of TLR4 in mice induced substantial reduction in lung fibrosis." (PMID 32973815, 2020). "In contrast to the WTI model, single deficiency of TLR4 in TLR4−/− mice also led to a massive inflammation and more pronounced pulmonary fibrosis upon intratracheal BLM application and this was linked to more pronounced lung dysfunction and increased death of the TLR4−/− mice compared to WT mice." (PMID 28836991, 2017). "The observed exacerbation of both, BLM and WTI-induced pulmonary fibrosis in TLR2−/−/TLR4−/− mice highlights that multiple and time-dependent signals seem to be required to shape an optimal immune response in order to orchestrate inflammation, resolution and regeneration." (PMID 28836991, 2017). "Indeed, inhibition of the NF-kappa B cascade aggravated the outcome of silica-induced lung fibrosis and TLR4 pathway activation reduced the amplitude of pulmonary fibrosis in mice exposed to silica." (PMID 25050810, 2014).
pulmonary fibrosis (continued). "Our previous studies have shown that LPS plays an important role in the development of acute lung injury (ALI), acute respiratory distress syndrome (ARDS), and pulmonary fibrosis, through activation of TLR4 and its downstream intracellular signal transduction pathways." (PMID 22563417, 2012). "Although the pro-inflammatory M1 macrophages are usually regarded as anti-fibrotic in lung fibrosis, they could exacerbate the inflammatory status of the lung injury and evoke the fibrotic response in lung fibrosis patients through activation of the TLR4 signaling." (PMID 36979493, 2023). "However, according to current evidence, the role of TLR4 in lung fibrosis is contradictory." (PMID 32679721, 2020). "Considering a recent report that the loss of RAGE contributes to pulmonary fibrosis, the increase of HMGB1 in alveolar fluids itself may induce fibrogenesis through other HMGB1 receptors, such as the Toll-like family of receptors (TLRs), TLR4, TLR2, or TLR9." (PMID 21637372, 2011). "Mechanistically, TP-TR downregulated the TLR4/TGF-β level to alleviate airway inflammation and pulmonary fibrosis, concurrently inhibiting MMP9/12 and MUC5AC/5B expression, thereby delaying lung tissue destruction and reducing mucus production." (PMID 40845001, 2025). "Bacterial infection significantly promotes the progression of pulmonary fibrosis through the activation of multiple critical signaling pathways, such as the TGF-β/Smad signaling pathway, and TLR4/NF-κB inflammatory pathway." (PMID 40963564, 2025). "As discussed under the “TGFβ signaling pathway,” soluble decorin is an endogenous ligand to TLR2 and TLR4 and can activate the p38 MAPK and ERK pathways, promoting inflammation and lung fibrosis and acting as a DAMP." (PMID 36835058, 2023). "In a study on the construction of a mouse model of idiopathic pulmonary fibrosis based on bleomycin (BLM), Astragalus polysaccharide was found to attenuate the inflammatory response by inhibiting the TLR4/NF-κB signaling pathway." (PMID 38054830, 2023). "As downstream signaling pathways of TLR4, MAPK family, NF-κB and IRF3 have been reported to regulate cell growth and inflammation, leading to pulmonary fibrosis 74-76." (PMID 33746598, 2021). "The role of TLR4-activating DAMPs in pulmonary fibrosis has been further evaluated with high-mobility group box1 (HMGB1), a potent inducer of TLR4 in pulmonary fibrosis." (PMID 34258628, 2021). "The AOP 347 suggests that the combination of two different MIEs, including the activation of toll-like receptor 4 (TLR4) as well as the inactivation of PPAR-γ, promotes pulmonary fibrosis as a cocktail effect." (PMID 33809804, 2021). "In the two intersecting AOPs (AOP 347), TLR4 activation and PPAR-γ inactivation were suggested as the MIE of pulmonary fibrosis." (PMID 33809804, 2021). "We showed that TLR4, MD2, Myd88, and related pathways are significantly induced in lungs collected on day 14 of bleomycin-induced pulmonary fibrosis." (PMID 34367191, 2021). "Raltegravir ameliorated pulmonary fibrosis by reducing the pathology score, collagen deposition, and expression of α-smooth muscle actin, NLRP3, HMGB1, TLR4, inhibitor of kappa B, p-NF-κB, HIF-1α, collagen I, and collagen III." (PMID 31481891, 2019). "The nucleotide-binding oligomerization domain-like receptor 3 (NLRP3) inflammasome and HMGB1/toll-like receptor 4 (TLR4) play vital roles in inflammation and pulmonary fibrosis, and NLRP3 is a key regulator of HMGB1 release." (PMID 31481891, 2019). "Furthermore, LPS-pretreated WT, but not TLR4-deficient, iNKT cells suppressed pulmonary fibrosis, but worsened hypersensitivity pneumonitis more than untreated WT iNKT cells, indicating that exogenous TLR4 ligands regulate iNKT cell functions in pulmonary diseases." (PMID 23028952, 2012).
pulmonary fibrosis (continued). "Because TLR4 is a key point in the first step of the LPS signal transduction pathway, inhibiting TLR4 expression and the subsequent blocking of its signal pathway may represent an effective way to ameliorate the acute inflammatory reaction and pulmonary fibrosis that occur during ALI." (PMID 20017955, 2009). "Studies have shown that 4 weeks of moderate-intensity aerobic exercise suppresses the expression of TGF-β1 and inflammatory pathways TLR4/TNF-α and SRB/NLPR3, which, in turn, suppresses the expression of macrophage-derived IL-17A, thereby ameliorating silica-induced pulmonary fibrosis." (PMID 39796197, 2025). "Another regulatory mechanism through which tectorigenin might inhibit pulmonary fibrosis can be orchestrated by modulating the transforming growth factor (TGF)‐b1/Smad and toll‐like receptor (TLR)‐4/NF‐ĸB signaling pathways." (PMID 38664220, 2024). "In a BLM (BLM)-based mouse model of idiopathic pulmonary fibrosis (IPF), Astragalus polysaccharides were found to attenuate the inflammatory response by inhibiting the TLR4/NF-κB signalling pathway and to balance the gut microbiota by regulating metabolic pathways." (PMID 38054830, 2023). "HMGB1 may induce apoptosis resistance of fibroblasts via activating Toll like receptor 4 (TLR4) by NF-κB and PI3K/Akt signaling, leading to persistent pulmonary fibrosis." (PMID 35111363, 2022). "Thus, in contrast to the protective action of TLR4, TLR2 has disease-promoting effects in the acute model of BLM-induced pulmonary fibrosis." (PMID 28836991, 2017). "TLR4-shRNA lentivirus infection may inhibit the expression of α-SMA and type I procollagen and therefore alleviate the degrees of pulmonary fibrosis induced by LPS." (PMID 20017955, 2009). "Thus, Gal-3, TLR4, and TREM2 have a potentially major role in lung fibrosis post-viral infection." (PMID 38540252, 2024). "On the other end, in its soluble form, decorin is an endogenous ligand to TLR2 and TLR4 and can activate the p38 MAPK and ERK pathways, leading to pro-inflammatory signaling; it may also promote lung fibrosis when degraded by cathepsin-S because fragmentation disrupts its anti-fibrotic capabilities." (PMID 36835058, 2023). "In this experiment, the expression of TLR4 in mouse lung tissue increased significantly 72 hours after LPS treatment and was accompanied by increased expression of α-SMA, type I procollagen, and PICP; moreover, the degree of pulmonary fibrosis became intense 4 weeks after LPS challenge." (PMID 20017955, 2009). "In this experiment, we used an in vivo experiment to show that TLR4 could activate the PI3K-Akt pathway and upregulate expression of integrin β1, thereby promoting fibroblast activation and collagen secretion and initiating pulmonary fibrosis at the early stage of ALI." (PMID 20017955, 2009). "It remains possible that the TRPV4 interacting partners are not TLR4-dependent, as other data suggests that TRPV4 interacts with PI3K to mediate pulmonary fibrosis." (PMID 32676078, 2020).
necrotizing enterocolitis (70 papers, 2010 to 2025). Necrotizing enterocolitis (NEC) is a devastating disease that affects mostly the intestine of premature infants. "In a preclinical model of necrotizing enterocolitis, loss of TLR4 in enteric glia prevented the loss of these cells and avoided GI dysmotility." (PMID 41261342, 2025). "HMOS, including 2′FL and 6′SL, directly bind to TLR4 and suppress TLR4-mediated NF-κB signaling to prevent necrotizing enterocolitis, a major cause of mortality in preterm infants." (PMID 35203555, 2022). "For example, dysregulated intestinal TLR4 activation generates chronic inflammation and intestinal epithelial apoptosis in the setting of necrotizing enterocolitis (NEC), the current leading cause of death among preterm infants." (PMID 29017607, 2017). "In this context, it is interesting that failure to downregulate TLR4 signaling and therewith an excessive IL-8 response in preterm infants has been associated with the development of necrotizing enterocolitis (NEC)." (PMID 28432664, 2017). "Despite the hypo-responsiveness of TLR4 in various intestinal epithelial cells, uncontrolled TLR4 activation is associated with necrotizing enterocolitis." (PMID 22570785, 2012). "Increased TLR4 expression has been linked to several conditions, including hypoxia‐induced damage to intestinal barrier function and bacterial translocation, necrotizing enterocolitis, systemic inflammation induced by the chemotherapy drug doxorubicin, and neuroinflammation triggered by LPS." (PMID 41261342, 2025). "Furthermore, TLR4 has been implicated in necrotizing enterocolitis and necrotizing enterocolitis–linked lung injury." (PMID 35471950, 2022). "In the context of necrotizing enterocolitis (NEC), the leading cause of death from gastrointestinal disease in preterm infants, the role of TLR4 has furthermore been studied in mice models and in vitro experiments." (PMID 24039130, 2013). "The 6′-SL and 2′-FL have previously been shown to protect against necrotizing enterocolitis (severity) by reducing inflammation through inhibition of the Toll-like receptor 4 activation pathway." (PMID 39726867, 2024). "In human infant and mouse intestinal explants, 2′-FL decreased the severity of necrotizing enterocolitis by binding to the TLR4-myeloid differentiation factor 2-[MD2] complex, which prevented lipopolysaccharide (LPS) binding." (PMID 39525504, 2024). "TLR4, which contributes to the occurrence of intestinal inflammation and necrotizing enterocolitis (NEC), can be inhibited by msEVs." (PMID 37242660, 2023). "Consistent with this study, glycyrrhizin inhibited the expression of TLR4 and NF‐κB in necrotizing enterocolitis rats." (PMID 34953035, 2022). "Inhibition of HMGB1 was found to improve intestinal inflammation in necrotizing enterocolitis by inhibiting NLR pyrin domain containing 3 via the TLR4 and NF-κB signaling pathways." (PMID 35335612, 2022). "For example, the TLR4 antagonist C34 has already demonstrated efficacy in necrotizing enterocolitis." (PMID 36551259, 2022). "Necrotizing enterocolitis (NEC) is a catastrophic disease largely occurring in preterm infants, and toll-like receptor 4 (TLR4) has been implicated in its pathogenesis." (PMID 36299988, 2022). "Necrotizing enterocolitis (NEC) is a disease of prematurity requiring Toll-like receptor 4 (TLR4) activation on the gut epithelium." (PMID 33589625, 2021). "We know that upregulated Toll-like receptor 4 (TLR4) in the intestinal epithelium plays a key role in the inflammatory condition of preterm infants, such as necrotizing enterocolitis (NEC)." (PMID 33785826, 2021). "Endothelial TLR4 activation impairs intestinal microcirculatory perfusion in necrotizing enterocolitis also via eNOS-NO-nitrite signaling (endothelial nitric oxide synthase)." (PMID 33738273, 2020).